TTK (TTK protein kinase)
Diseases named in the same sentence as TTK in open-access papers (continued):
Sharing a sentence is not in itself a finding about the gene and the disease.
tumor (continued). "Overexpression of TTK is associated with high serum AFP (alpha-fetoprotein) levels, large tumor size, advanced TNM stage (tumor, nodes, and metastases), and distant metastases." (PMID 36405310, 2022). "A variety of TTK inhibitors have been developed to improve the effectiveness of tumor therapy or overcome drug resistance." (PMID 35850753, 2022). "Nevertheless, although not reaching significance, there was a trend of reduced expression of PLK1, KIF11, PTTG1 and TTK (the latter otherwise induced by DEXA in U25MG cells in DEXA treated tumours." (PMID 33478100, 2021). "ISG15, CDC20, TTK, and NCAPG expression showed positive correlations with tumor mutational burden and neoantigen load in BC patients." (PMID 34733851, 2021). "Therefore, TTK may be a tumor promoter and cisplatin-resistance associated factor." (PMID 34598710, 2021). "Relative to control cells, the suppression of all three genes (TTK, TPX2, and RAD54B) was associated with significant reduction in tumor size (p ≤ 0.04) in SCID mice." (PMID 34031527, 2021). "In vivo, TTK knockdown inhibited tumor growth and increased cisplatin sensitivity by inhibiting the autophagy pathway." (PMID 34876569, 2021). "The expression level of TTK was verified by immunohistochemistry (IHC) and real-time quantitative polymerase chain reaction (RT-qPCR), and the tumor-promoting effect of TTK in BC cells was confirmed in vitro." (PMID 34988018, 2021). "From 370, 445, and 455 different tumor studies, TTK, NEK2, and CDK1 gene expression data were collected." (PMID 34072728, 2021). "IHC staining of the tumor showed that TTK knockdown reduced the levels of Ki67 and LC3B and increased the level of cleaved caspase-3, especially when administered in combination with cisplatin treatment." (PMID 34876569, 2021). "Small-molecule inhibitors of TTK and other genes identified in this study have the potential to inhibit/delay genomic evolution and tumor growth." (PMID 34031527, 2021). "In conclusion, we found that CENPF, BUB1, BUB1B, KIF23 and TTK were potential key genes involved in regulating hypoxia induced tumor cell stemness." (PMID 33148251, 2020). "The frameshift mutations of mitotic checkpoint kinase TTK in CRC with microsatellite-unstable are frequent and tend to prompt tumor growth because of a triggered alteration in the cell cycle." (PMID 33134313, 2020). "Collectively, these results indicated that overexpression of TTK was beneficial for cell proliferation and tumor growth." (PMID 32530571, 2020). "The protein expression levels of TTK were increased in NSCLC tumor tissues and inhibition of TTK reduces A549 cell proliferation, migration and tumorigenesis." (PMID 32969465, 2020). "Knockdown of TTK protein inhibits the activation of Akt‐mTOR signaling pathway and reveals the mechanism of TTK involvement in tumor formation." (PMID 32530571, 2020). "The tumor volume of TTK-knockdown A549 were smaller than the tumor of control A549 after 52-days observation." (PMID 32121246, 2020). "We observed that TTK expression was negatively correlated with survival and tumor recurrence in vivo." (PMID 32530571, 2020). "We also found that overexpression of TTK promoted cell proliferation, and inhibition or knockdown of TTK promoted apoptosis, indicating that TTK plays a role as an oncogene during tumor formation." (PMID 32530571, 2020). "TTK contributes to the proliferation and invasion of tumor cells via regulating the mitotic process." (PMID 33061942, 2020). "Our results indicate that TTK regulates the proliferation and apoptosis of tumor cells through Akt‐mTOR signaling pathway." (PMID 32530571, 2020). "Both in the dataset GSE25055 and GSE42568, higher expression levels of ASPM, CDC20, and TTK were related to advanced tumor grades." (PMID 31106147, 2019). "In this manner, the tTK gene would allow us to selectively “kill at will” replicating tumor cells that activated the GSC specific promoters." (PMID 31267022, 2019).
tumor (continued). "In the datasets GSE25055 and GSE42568, higher expression levels of ASPM, CDC20, and TTK correlated with advanced tumor grades." (PMID 31106147, 2019). "We found TNBC cell lines exhibited the highest levels of TTK, while knockdown of TTK increased apoptosis and prevented tumor growth." (PMID 30206215, 2018). "A logical next step based on our results would be to look at targeting aneuploid stable tumours and CIN tumours with TTK inhibitors in vivo." (PMID 28415765, 2017). "Our results are in agreement with prior reports in other tumor types where either pharmacologic inhibition or genetic knockdown of TTK resulted in a similar decrease in the growth of multiple cancer cell lines." (PMID 28380042, 2017). "TTK inhibition reduced tumour growth in five studies using xenografts models of chromosomally stable or low-CIN cell lines (i.e., HCT 116, HeLa, MDA-MB-231 and A2780)." (PMID 28415765, 2017). "We show that treatment of tumor cells with the selective small molecule TTK inhibitor NTRC 0066-0 overrides the mitotic checkpoint, irrespective of cell line sensitivity." (PMID 28415765, 2017). "For the first time we studied here the effect of a TTK inhibitor on the viability and proliferation of primary human patient-derived tumor cell samples and organoids." (PMID 28415765, 2017). "We have identified RSK and TTK as potential targets for antiangiogenic tumor therapy, and provide an assay system for further pathway screens." (PMID 27618721, 2016). "Subsequent pathology staining provided further clear evidence confirming the in vivo anti-tumor activity of in-vivo gene silencing of TTK." (PMID 27618777, 2016). "Tumor volumes were smaller in TTK KD s120 group as compared to the control (Ctrl) siRNA group, showing a trend towards inhibition of in-vivo HCC growth by such in vivo TTK siRNA." (PMID 27618777, 2016). "Presumably, these low-TTK expression albeit still histologically tumor-free tissues show a field effect and suggest early involvement of TTK in hepatocarcinogenesis." (PMID 27618777, 2016). "In HCC, TTK is overexpressed and correlated with age, HBsAg, Edmondson tumour grade and satellite lesion." (PMID 26418879, 2015). "In 20 cases of HCC tumor specimens, TTK mRNA expressions were dramatically increased, comparison to their paired adjacent non-tumor specimens." (PMID 26418879, 2015). "Elevated TTK expression positively correlated with large tumor size and presence of the portal vein tumor thrombus (PVTT)." (PMID 26418879, 2015). "Our data suggest that depletion of TTK would selectively impair growth of rapidly dividing cells, one of the hallmarks of tumor cells." (PMID 23700430, 2013). "In agreement with others studies performed on tumor cell lines of various origins, we found that the RNAi-mediated depletion of TTK severely compromises the viability of human TNBC cells." (PMID 23700430, 2013). "Some tumor cells showed a cytoplasmic and nuclear staining for TTK, consistent with the fact that TTK expression is highly regulated during cell cycle progression, with a peak in G2/M phase." (PMID 23700430, 2013). "In fact, they were strongly induced by smoking in the early stage tumor tissue and some, e.g., NEK2 and TTK, were also associated with increased mortality risk." (PMID 18297132, 2008). "TTK overexpression has been reported in different tumour types, including BC." (PMID 39775836, 2025). "Targeted inhibition of TTK exerted anti‐tumor effects both in vitro and in vivo." (PMID 39836493, 2025). "Immunohistochemical experiments on tumor tissues showed that TTK knockdown suppressed the expression of the tumor proliferation index Ki67 and autophagy marker LC3B, while increasing the level of the apoptosis marker caspase-3, especially when combined with cisplatin treatment." (PMID 38601753, 2024). "Indeed, proteomic analysis showed overexpression of tumor-related proteins such as TTK, MTA or MDR1." (PMID 39114302, 2024).
tumor (continued). "Additionally, we assessed the relationship between TTK expression and 28 tumor-infiltrating lymphocytes (TILs) in the TISIB." (PMID 38195567, 2024). "According to some research, combining TTK inhibitors with chemotherapeutic drugs may significantly boost the effectiveness of destroying tumor cells." (PMID 36829176, 2023). "After the detection of hub genes utilizing the PPI network of common upregulated genes, the top five hub genes, including AURKA, AURKB, KIF20A, MELK, and TTK that played the most critical role in both primary tumor cell and P7731 cell line, were selected to validate the study." (PMID 37231064, 2023). "In conclusion, TTK might be a potent regulator for tumor progression by the efficient bioinformatics approaches and validated by the in vitro experiments." (PMID 37815894, 2023). "High expression of TTK inhibited cell apoptosis, thereby leading to tumor enlargement." (PMID 36849137, 2023). "In addition, the expression level of TTK is correlated with some tumor infiltrating cells and is positively correlated with TMB." (PMID 35784389, 2022). "Overexpression of TTK may be one of the important mechanisms for resistant tumor cells to live with aneuploidy." (PMID 34598710, 2021). "TTK knockdown or cisplatin treatment alone reduced the tumor volume, and the combination treatment led to a more obvious decrease in the tumor volumes and tumor weight." (PMID 34876569, 2021). "CDK1, HMMR, PTTG1, and TTK were positively correlated with tumor-infiltrate lymphocytes, which might involve tumor immune response." (PMID 34187556, 2021). "At last, we checked the protein expression distribution of these genes in The Human Protein Atlas, TTK and CYP3A4 were found to be differentially expressed in tumor and normal tissues, which TTK was overexpressed in HCC and the expression of CYP3A4 was found decreased in HCC." (PMID 34257549, 2021). "Furthermore, we report that TTK regulates the proliferation and apoptosis of tumor cells through the Akt‐mTOR pathway." (PMID 32530571, 2020). "Knockdown of TTK or treatment with a TTK inhibitor could suppress tumour growth by inhibiting cell proliferation, migration, and tumorigenesis." (PMID 33282948, 2020). "TDRD6 and TTK are promising T cell and B cell targets for tumor vaccines." (PMID 32728493, 2020). "Inhibition of TTK resulted in chromosome mis-segregation and tumor cell death." (PMID 31106147, 2019). "On the basis of these tumor-promoting roles, TTK is an attractive therapeutic target." (PMID 30206215, 2018). "TTK, AURKA, BUB1, CDK1 and NEK2 were fundamental kinases with high node degree, which may be required for maintaining the molecular signals underlying tumor progression." (PMID 30598639, 2018). "Our results suggest that TTK inhibitor therapy could be a new suitable treatment option in particular at the first two tumor stages, where CIN remains minimal." (PMID 28415765, 2017). "Since the tetraploids show low level resistance against various cytotoxic drugs and several targeted therapies, TTK inhibitors may be a better choice for the eradication of tumor cells that underwent whole genome doubling." (PMID 28415765, 2017). "To determine whether the inhibition of RSK and TTK inhibits neovascularization in vivo, we gave mice LL/2 tumor grafts." (PMID 27618721, 2016). "An elevated TTK expression was observed in these 3 cases of HCC tumor specimens." (PMID 26418879, 2015). "Furthermore, the size and weight of these xenograft tumors also showed that TTK downregulation significantly suppressed tumorigenesis when sorafenib was administrated on mice with tumor burden." (PMID 24905462, 2014). "Furthermore, the TTK inhibitor CFI-402257 effectively suppressed tumor growth in vivo, suggesting that targeting TTK may offer a promising approach for BC treatment." (PMID 40269198, 2025). "Furthermore, TTK contributes to tumor growth and metastasis in mouse ccRCC." (PMID 36941564, 2023).
tumor (continued). "Therefore, TTK inhibitors could be used with existing anti-tumor drugs or radiation therapy to enhance tumor destruction." (PMID 36829176, 2023). "Given that dysregulation of TTK expression is closely correlated with malignant proliferation of tumor cells and consequently increased tumor purity, we speculated that TTK might alter the proportion of cells in the tumor microenvironment." (PMID 36829176, 2023). "TTK could affect the tumor microenvironment (TME) by affecting the number of immune cells." (PMID 36910651, 2023). "Moreover, our findings hinted at the tumor-promoting functions of TTK in EC." (PMID 36829176, 2023). "This suggests that CWH43’s tumor-suppressing potential might act via TTK modulation." (PMID 37894942, 2023). "Therefore, TTK is likely to become a LUAD tumor therapeutic target and prognostic marker." (PMID 35784389, 2022). "High TTK expression may help tumours overcome the challenges of an oxidative microenvironment." (PMID 33282948, 2020). "Therefore, we investigate whether TTK protein regulates proliferation and apoptosis of tumor cells by modulating the Akt‐mTOR signaling pathway." (PMID 32530571, 2020). "It is thus likely that targeting TTK could attenuate tumor progression." (PMID 30206215, 2018). "Thus, the differences that we found between normal and tumor cells in cell cycle progression and induction of apoptosis upon TTK depletion might reflect differences in genomic background." (PMID 23700430, 2013). "TTK inhibitor, CFI‐402257, exerted anti‐tumor effects in TCL and synergized with the PI3K inhibitor Duvelisib." (PMID 39836493, 2025). "Inhibition of TTK, by either knockdown or specific inhibitor CFI‐402257, exerted anti‐tumor effects in vitro and in vivo." (PMID 39836493, 2025). "Inhibition of TTK, by either knockdown or specific inhibitor CFI‐402257, exerts anti‐tumor effects in vitro and in vivo." (PMID 39836493, 2025). "Though we have unveiled CWH43’s tumor-suppressing role in CRC and its potential interaction with TTK, the exact mechanisms remain elusive." (PMID 37894942, 2023). "Four hub genes, including TTK, BUB1B, NUSAP1, and ZWINT, were revealed as tumor-promotive factors in OC, having the potential to be utilized as novel biomarkers and therapeutic targets for OC management." (PMID 37304238, 2023). "Tumor cells and patient-derived xenografts (PDXs) sensitive to AURKB and TTK inhibitors consistently showed high expression levels of BH3-interacting domain death agonist (BID), while cell lines and PDXs with low BID were uniformly resistant." (PMID 37443114, 2023). "Indepth evaluation of three genes (TTK, TPX2 and RAD54B) confirms their role in genomic instability and tumor growth." (PMID 34031527, 2021). "Finally, after a series of screening and verification tests, we identified a threonine and tyrosine kinase (TTK) gene that can indeed promote tumor progression and predict the prognosis of BC, and we revealed that TTK may be a potential indicator of the changes in the TME in BC." (PMID 34988018, 2021). "•Preclinical study: TTK inhibitors have anti-proliferative effects; combination of BOS172722 and paclitaxel results in significant tumor regression compared with either drug alone." (PMID 34778045, 2021). "There is no staining of TTK, CCNB1, and CCNB2 in normal human lung tissues; however TTK, CCNB1, and CCNB2 showed strong positive in NSCLC tissues; the majority of positive cells were tumor cells and immune cells." (PMID 32969465, 2020). "In summary, we confirmed TTK, CCNB1 and CCNB2 were pro-oncogenes that mainly expressed in tumor cells and immune cells." (PMID 32969465, 2020). "We found that the protein of TTK, CCNB1, and CCNB2 much stronger expressed in tumor cells and immune cells in NSCLC when compared with that in normal lung tissues." (PMID 32969465, 2020). "We designed a strategy to express in all tumor cells PLuc and eGFP reporters and, RLuc, RFP and tTK genes in the subpopulation of GSCs with active CD133 or OCTA4/SOX2 promoters." (PMID 31267022, 2019).
tumor (continued). "TTK, also known as monopolar spindle 1 (MPS1), plays a key role in cancer cell growth and proliferation, with its inhibition able to decrease tumor aggressiveness." (PMID 30886771, 2019). "Six genes (67%) tended to be highly expressed in POLE-category tumours, with DEPDC1 and TTK genes in particular exhibiting significant differences in expression." (PMID 29880869, 2018). "This study provides evidence for the role of TTK in EMT and subsequent tumor progression and metastasis." (PMID 30206215, 2018). "When the Wilcoxon signed-rank test was used, we noted that 6 of 18 (33%) CTAs tested, MAGEA3, OIP5, TTK, PLU1, DKKL1, and FBXO39, were significantly (p < 0.05) overexpressed in the tumor compared with normal tissue located ~5 cm away from the primary lesion." (PMID 27635108, 2016). "The strong expressions of URLC10, TTK and KOC1 antigens were observed in cytoplasm of tumor cells of all patients." (PMID 24708624, 2014). "The expressions of HLA class I, URLC10, TTK, KOC1, VEGFR1 and VEGFR2 antigens were observed in the tumor tissues of all patients." (PMID 24708624, 2014). "We established that both, tTK activity in genetically modified hAMSCs, and administration of GCV were both required for bystander killing of tumor cells co-cultivated with hAMSCs." (PMID 22529983, 2012). "This might be due to the fact that the level of TTK was already extremely high in PDAC, and its ability to promote tumor progression was saturated." (PMID 38711083, 2024). "In addition, preclinical studies with a selective TTK inhibitor (CFI-402,257) showed decreased proliferation of ER+/HER2− cell lines and suppressed tumor growth in patient-derived xenografts." (PMID 38886738, 2024). "As the expression of ANXA2 and TTK is up-regulated in clinical tumor specimens, and they are both closely related to high tumor stage and poor prognosis, targeting ANXA2 and TTK may be new therapeutic strategies for ESCC." (PMID 38658569, 2024). "Additionally, the orally active small molecule inhibitor of TTK (CFI-402,257) effectively inhibits tumor growth and promotes the action of immune cells." (PMID 38195567, 2024). "Furthermore, we demonstrate that TTK has a differential relationship with survival dependent on HPV status, advanced tumor stage, and addition of radiotherapy." (PMID 39392349, 2024). "Since PLK1 and TTK had almost no expression, the remaining 5 functional and 2 prognostic MCGs were compared between high/low MC tumor cells." (PMID 39015573, 2024). "The tumor volumes in cells transfected with PCMV TTK were significantly larger than those in cells transfected with PCMV control, indicating the TMZ resistant function of TTK in vivo." (PMID 35850753, 2022). "For LIHC, gene TTK was identified as a P-LNE biomarker, and TTK alone or in combination with other therapeutics might be able to selectively kill tumor cells." (PMID 35668489, 2022). "In LIHC, TTK was identified as a P-LNE biomarker, and TTK alone or in combination with other therapeutics may selectively kill tumor cells." (PMID 35668489, 2022). "However, BUB1, CCNB1, BUB1B, KIF11, CDC20, TTK, and NCAPG, which are closely related to regulation of the cell cycle and DNA repair, showed strong positive correlations with tumor purity in luminal-type BC." (PMID 34733851, 2021). "KLF5 function could be context-dependent, including a role in TTK-mediated EMT due to specific cell signaling, tumor microenvironment, and the subtype of TNBCs." (PMID 30206215, 2018). "We noted that tumor tissues had positive staining of TTK, whereas tumor-free liver tissues were totally or nearly absent of TTK." (PMID 27618777, 2016). "In fact, 55.5% and 44.4% of tumor samples with a weak HMGA1 staining (1+) had negative or weak staining also for BUBR1 and TTK respectively, whereas 61.5% and 66.7% of tumor samples with a strong HMGA1 immunoreactivity (3+) had also a strong immunoreactivity for BUBR1 and TTK, respectively." (PMID 26009897, 2015).